GPNMB (glycoprotein nmb)
Diseases named in the same sentence as GPNMB in open-access papers (continued):
Sharing a sentence is not in itself a finding about the gene and the disease.
tumor (continued). "The tumor-killing effect of GPNMB-targeting ADC was based on low expression of surface GPNMB in normal cells but high expression of GPNMB in cancer cells." (PMID 34108545, 2021). "The role of GPNMB is already well-established in tumour progression, where over-expression of the gene suppresses the immune response to tumour growth." (PMID 33417599, 2021). "In our study, we found high GPNMB level is correlated with low histologic grade or well differentiated tumor, whereas depletion of GPNMB lead to high histologic grade or less differentiated tumor." (PMID 34108545, 2021). "We further demonstrated that CD44 engagement by GPNMB activates in tumor cells the expression of several factors, including chemokines, e.g.: CXCL1, CXCL2, CCL2, CCL5, CCL7, cytokines: IL-6, IL-11, IL-33, and the IL-33 receptor: IL-1RL1, also named ST2." (PMID 34583655, 2021). "Of the 1172 (77%) patients for whom tumor tissue was provided and adequate for gpNMB expression testing, 650 (55%) had tumors overexpressing gpNMB (i.e., ≥25% cells positive)." (PMID 34016993, 2021). "In primary methylcolantrene-induced fibrosarcoma, soluble GPNMB released by macrophages binds to the CD44 receptor on tumor cells and triggers the proliferation of CSCs." (PMID 34583655, 2021). "In mouse tumor models, we have recently reported that macrophage-derived soluble GPNMB triggers the expansion of cancer stem cells growing in vitro as self-renewing spheroids." (PMID 34583655, 2021). "Another promising strategy is glembatumumab vedotinb, a monoclonal antibody-drug conjugate against the a transmembrane glycoprotein gpNMB, overexpressed by multiple tumor types, including MM." (PMID 32825562, 2020). "While nine (38%) tumor samples showed paradoxical increases in GPNMB expression, three (13%) had a decreased expression from baseline." (PMID 32823698, 2020). "Cell function experiments and xenograft tumors were conducted in vivo to further verify the role of GPNMB in tumor progression." (PMID 32833670, 2020). "GPNMB expression was assessed pre- and post-treatment via immunohistochemistry for patients with available tumor tissue." (PMID 32823698, 2020). "Increased expression of KLRC1, CCL5, PLP1, CD163, MSR1, and GPNMB was found following treatment and tumor recurrence." (PMID 30151353, 2018). "We have established in this study the tumor suppressor status of GPNMB gene in colon oncogenic transformation." (PMID 30400781, 2018). "We reported that reduced GPNMB gene expression was correlated with high-grade tumor and metastasis in CRC." (PMID 30400781, 2018). "Previous studies demonstrated that dysfunction of GPNMB has an important regulatory role in alteration of cellular function in tumor cells." (PMID 30484490, 2018). "Overall, these studies are indicative of tumor suppressor activities of GPNMB in CRC cell lines experiments." (PMID 30400781, 2018). "Mean SUV of the [89Zr]DFO-CR011 tumor uptake was correlated with total gpNMB expression obtained from ELISA." (PMID 29262642, 2017). "The role that microglia plays in GBM tumor progression was verified by the identification of protumorigenic Osteoactivin (GPNMB) and Osteopontin (SP1) expression in profiled GBM tumor-associated microglia." (PMID 28299344, 2017). "The efficacy of CDX-011 is being compared to capecitabine in the ongoing phase II METRIC trial in patients with TNBC positive for gpNMB in >25% of tumor epithelium by IHC of an archival tumor material (NCT#01997333)." (PMID 29262642, 2017). "GPNMB subcellular localization, however, tends to be restricted to intracellular compartments in normal cells, while being enriched on the cell surface in tumor cells." (PMID 26700623, 2016). "We found that the expression of GPNMB and SPP1 was significantly higher in human GAMs isolated from GBM samples, when compared to non-tumor-associated control microglia and blood monocytes." (PMID 25658639, 2015).
tumor (continued). "Of six HER2-positive BC patients with high GPNMB levels (>15 ng/mL), five samples showed GPNMB expression in tumor cells." (PMID 26077887, 2015). "On the other hand GPNMB represents a molecule that suppresses T cell responses and permits tumor escape." (PMID 25889792, 2015). "To confirm GPNMB expression in tumor cells, we also performed immunohistochemistry using 10 surgical/biopsy specimens for the HER2-positive group." (PMID 26077887, 2015). "The source and rate of expression of GPNMB seems to be dependent on the grade of malignancy of the tumor." (PMID 25658639, 2015). "Of interest is the observation that tumor–derived endothelial cells express high levels of GPNMB/OA relative to endothelial cells derived from normal tissues." (PMID 20711474, 2010). "Our data suggests that GPNMB/OA-dependent augmentation of tumor growth is attributed to decreased apoptosis and increased angiogenesis in GPNMB/OA expressing tumors." (PMID 20711474, 2010). "To better characterize the functional role of GPNMB/OA in promoting tumor growth, we removed the primary tumors and subjected them to IHC analysis to assess differences in proliferation, apoptosis and angiogenesis." (PMID 20711474, 2010). "Notably, MES-like tumor cells and GPNMB+ MDMs were predominantly localized to peri-necrotic regions, whereas ICAM1+ MDMs, COL6A3+ TAFs, and endothelial cells were enriched in peri-vascular areas." (PMID 41174767, 2025). "Compared to GPNMB-, GPNMB+ cells exhibited significantly longer latency of tumor formation, measured by either time to palpability or time to tumor resection (volume of ~0.3 cm3) but earlier latency of lymph node invasion, consistent with their less proliferative and more invasive phenotype." (PMID 40528051, 2025). "Furthermore, we found that MES-like tumor cells and GPNMB+MDMs co-localize in the PAN region, whereas COL6A3+TAFs and ICAM1+MDMs are distributed adjacent to MVP niches for the first time, revealing the unique spatial ecological niches in GBM patients." (PMID 41174767, 2025). "GPNMB has transformed from an initially identified tumor suppressor to a key oncogenic driver." (PMID 41180454, 2025). "GPNMB orchestrates an immunosuppressive tumor microenvironment through dual mechanisms." (PMID 41180454, 2025). "Future studies should aim at validating GPNMB and CHI3L1 not only as markers of OCSC but also as causal players in OCSC-driven tumor progression and as putative targets in the context of tumor-eradicating strategies based on the elimination of the cancer stem cell subpopulation." (PMID 40204276, 2025). "However, in tumor tissues, GPNMB can promote the growth, proliferation, and metastatic invasion of various cancer cells, as well as enhance angiogenesis in the surrounding tumor environment." (PMID 41180454, 2025). "Moreover, increasing evidence suggests that GPNMB plays a role in suppressing the immune system in cancer, thus promoting tumor progression." (PMID 40528051, 2025). "Similarly, depletion of GPNMB in Raw264.7 macrophages or SIM-A9 microglia significantly extended survival of CT2A tumor-bearing mice." (PMID 40626360, 2025). "GPNMB can promote the polarization of macrophages toward the M2 phenotype, suppress proinflammatory cytokine production upon LPS stimulation, and enhance tumor migration and invasion in cancer." (PMID 40038549, 2025). "To confirm whether GSC stemness is involved in the impaired tumor progression upon GPNMB depletion in macrophages and microglia, we performed immunofluorescence staining for SOX2 in shC and shGPNMB tumors." (PMID 40626360, 2025). "Additionally, endothelial cells contribute to immune regulation; for example, in HCC, tumor endothelial cells (TECs) can induce CD8+ T-cell exhaustion through GPNMB expression, thereby impairing the immune system’s ability to combat tumors." (PMID 40299340, 2025). "In the tumor core, GPNMB was predominantly expressed by IBA1+ cells and only few IBA1− cells." (PMID 38566120, 2024).
tumor (continued). "Conversely, GPNMB can exhibit tumor-suppressive effects in certain contexts." (PMID 39263169, 2024). "The purpose of glembatumumab-vedotin is to attach gpNMB and, upon internalization, release MMAE by the breakdown of a valine-citrulline peptide linker that is susceptible to proteases, hence causing microtubule inhibition and tumor cell death." (PMID 39456611, 2024). "For instance, engineered senolytic EVs, conjugated with anti‐GPNMB antibodies and loaded with the combination drug D+Q, have demonstrated efficient and selective eradication of senescent tumour cells, thereby activating anti‐tumour immunity in a murine model." (PMID 39270064, 2024). "Based on the tumor promoting effect of GPNMB and its localization on the surface of tumor cells, targeting GPNMB and its mRNA as therapeutic intervention may inhibit the pulmonary cystic damage and tumor growth of LAM, and slow the progression of the disease." (PMID 39614360, 2024). "Targeting glycoprotein nonmetastatic melanoma protein B (GPNMB) could enhance tumor sensitivity to molecularly targeted therapies and create a more favorable environment for immune responses from T cells." (PMID 38720342, 2024). "GPNMB was overexpressed in the extracellular domain (ECD) of cancer cells of many malignancies, including melanoma, glioblastoma, and triple-negative breast cancer, and has been shown to be associated with tumor migration, invasion, and metastasis." (PMID 39614360, 2024). "The extracellular domain of GPNMB is found binding to several receptors on tumour cells." (PMID 38906852, 2024). "In normal, non-tumor brain tissue of murine and human origin, the expression level of GPNMB is low." (PMID 38566120, 2024). "GPNMB promotes proliferation, invasion and metastasis of tumor cells." (PMID 38566989, 2024). "Glycoprotein nonmetastatic melanoma protein B (GPNMB) is considered to associate with tumor initiation, metastasis and angiogenesis." (PMID 38140790, 2023). "GPNMB is also known to promote tumor initiation by increasing CSC formation and metastasis in TNBC." (PMID 36737605, 2023). "This evidence is likely the mechanism by which dasatinib increases gpNMB expression and sensitizes tumor cells to CDX-011 therapy and warrants further investigation to test this hypothesis." (PMID 36900378, 2023). "Moreover, GPNMB is essential for tumor-cell intravasation and extravasation in ASPS, given that Gpnmb knockdown significantly reduces the interaction between ASPS and endothelial cells." (PMID 37029109, 2023). "SLC30A10 and GPNMB were both related to tumor-promoting inflammation and tumor progression." (PMID 38110638, 2023). "We hypothesized that the tumor uptake of [89Zr]Zr-DFO-CR011 will increase in gpNMB-positive MDA-MB-468 xenograft models after treatment with dasatinib relative to baseline imaging." (PMID 36900378, 2023). "They found that GPNMB was significantly upregulated in PD-1-resistant tumour cells." (PMID 36090016, 2022). "GPNMB is a newly discovered tumour-promoting factor that may promote tumour cell progression by activating the PI3K/AKT pathway by EGFR." (PMID 36090016, 2022). "GPNMB was more highly expressed in metastatic lymph nodes than in the primary tumor." (PMID 36061142, 2022). "In contrast, there are few studies on GPNMB in tumour resistance." (PMID 36090016, 2022). "Macrophage in this cluster had high expression of type I interferon signaling related genes (IFITM3, IFI27, MX1, IFI6, and ISG15) as well as gene features related to immunosuppressive phenotype (APOE, APOC1, S100A9, and GPNMB), whereby participating in tumor immune regulation." (PMID 35265520, 2022). "As a tumour-promoting factor, GPNMB is expected to be a potential target for ESCC." (PMID 36090016, 2022).
tumor (continued). "An exploratory biomarker analysis from EMERGE also suggested that patients with advanced TNBC overexpressing gpNMB (i.e., ≥25% tumor epithelial cells staining positive by immunohistochemistry (IHC)) were most likely to derive greater benefit from GV, compared with standard chemotherapies." (PMID 34016993, 2021). "Although the precise mechanism of GPNMB underpinning the tumor cells remains unknown, there is an urge to find the therapeutic options for patients with TNBC29." (PMID 34108545, 2021). "This indicated GPNMB expression was enriched in low histologic grade TNBC tumor." (PMID 34108545, 2021). "GPNMB is a tumor cell surface marker that has the potential to promote tumor growth and invasion." (PMID 34108545, 2021). "Therefore, we can envisage a feed-forward loop where cancer cells stimulate in macrophages the production of GPNMB that binding to the CD44 receptor on tumor cells triggers the release of IL-33." (PMID 34583655, 2021). "In addition, the high GPNMB levels in STAD cells showed association with higher tumor growth rates and larger tumor weight." (PMID 32833670, 2020). "However, we observed a paradoxical increase in expression of GPNMB in 38% of the tumor tissues after one cycle of GV treatment." (PMID 32823698, 2020). "Furthermore, cell function experiments and xenograft tumors in vivo were performed to further verify the role of GPNMB in tumor progression, and the data analysis results were presented above." (PMID 32833670, 2020). "Concerning PCNSL, 30% (6/20) showed tumor cell expression of GPNMB." (PMID 32610669, 2020). "Moreover, this tracer has potential to visualize different levels of cell surface gpNMB expression on tumor cells." (PMID 33096754, 2020). "In baseline tissue, GPNMB was highly expressed across all metastatic tissues, with 11 (42%) out of 26 available tissues demonstrating expression in 100% of tumor cells, whereas 8 (31%) of 26 tissues exhibited expression in 20–95% of tumor cells." (PMID 32823698, 2020). "Growing evidence identified GPNMB as an attractive therapeutic target for tumor and cancer." (PMID 30671053, 2018). "The functional analysis established GPNMB as a potential tumor suppressor gene." (PMID 30400781, 2018). "gpNMB is expressed in ≥ 25% of tumor epithelial cells in about 40% of TNBC patients." (PMID 29262642, 2017). "However, a limitation of this study is that we were unable to assess the selectivity of [89Zr]DFO-CR011 for targeting gpNMB in the tumor versus gpNMB in normal organs, as the CR011 antibody binds selectively to human gpNMB." (PMID 29262642, 2017). "[89Zr]DFO-CR011 was also evaluated in patient-derived xenograft models of TNBC, where tumor uptake in vivo had a positive correlation with total gpNMB protein expression via ELISA (r = 0.79), despite the heterogeneity of gpNMB expression within the same group of PDX mice." (PMID 29262642, 2017). "The involvement of GPNMB/OA ECD protein in promoting enhancement of cell migration and adhesion may be relevant to the pro-tumor and/or pro-metastatic functions of GPNMB/OA." (PMID 26883195, 2016). "The information generated from the work may be relevant in assessing the pro-tumor and pro-metastasis functions of GPNMB/OA ECD protein that is shed into tumor tissues according to GPNMB/OA expression levels." (PMID 26883195, 2016). "In each of the lines that demonstrated a maintained complete response to glembatumumab vedotin (OS-2, OS-17, and OS-33), there is 2+ to 3+ staining for GPNMB by immunohistochemistry, although the percentage of cells positive is as low as 5% of tumor cells for one line." (PMID 26380223, 2015). "Furthermore, based on the results obtained from clinical samples, we examined the mechanism by which GPNMB contributes to tumor progression, assuming that a cross talk between GPNMB and HER2 exists through shared signaling pathways." (PMID 26077887, 2015).
tumor (continued). "It remains an interesting task to investigate the expression and function of GPNMB in other tumor entities in two respects: On the one hand GPNMB is a potential tumor-associated antigen that could be an attractive target for immunotherapeutic approaches." (PMID 25889792, 2015). "Moreover, the kinetics of tumor outgrowth correlated with the level of GPNMB/OA expressed in these cells." (PMID 20711474, 2010). "Our evidence of a high expression of GPNMB by TdEC suggests that GPNMB may be a tumor stroma receptor for SP, involved in tumor angiogenic events and in determining the distinctive features of tumor vasculature." (PMID 18447899, 2008). "GPNMB reactivity is non‐specific and cannot distinguish between FLCN‐mutated tumours and TFE3/TFEB RCCs, as well as various other TSC1/2/MTOR‐mutated tumours, but it may be diagnostically useful for screening for FLCN mutations that would help distinguish them from their mimics." (PMID 41384711, 2026). "The therapeutic targeting of GPNMB presents a fundamental biological conundrum, as this multifunctional glycoprotein plays essential roles in maintaining neural myelin homeostasis and osteogenesis while concurrently driving tumor immune evasion and metastatic progression." (PMID 41180454, 2025). "This suggests that GPNMB in the tumor vasculature may be a novel target for HCC treatment." (PMID 40097979, 2025). "Thus, here we provide valuable information that GPNMB regulation on MDSC may serve as a tumor‐targeting therapy for CAC." (PMID 38140790, 2023). "Thus, these proof-of-principle studies demonstrate that resident brain cell populations, i.e., astrocytes, microglia and neurons, account for GPNMB, apolipoprotein CII and VSIG4 expression, whereas only GPNMB was expressed in a significant fraction of PCNSL by the tumor cells." (PMID 32610669, 2020). "GPNMB (also called Osteoactivin) is a transmembrane protein, but is also localized in the phagosome and can also be secreted, and might have different functions in GAMs and in the tumor." (PMID 25658639, 2015). "Finally, although GPNMB blockade modestly extends the survival of tumor-bearing mice, combining GPNMB inhibition with standard-of-care therapies (e.g., radiotherapy and chemotherapy) or targeting the downstream PYK2/RSK2 signaling axis may enhance translational relevance and therapeutic efficacy." (PMID 40626360, 2025). "Previous studies have proven that SREBF1, GPNMB, and HIF1A can promote primary tumor growth in a variety of cancers." (PMID 40095604, 2025). "Specifically, GSCs educate macrophages and microglia to preferentially express and secrete GPNMB in the GBM TME, which, in turn, promotes tumor progression." (PMID 40626360, 2025). "The results demonstrated significant co-localization of GPNMB+ MDMs and MES-like tumor cells, primarily within the PAN region, both in GBM patients and in patients who did not respond to neoadjuvant therapy." (PMID 41174767, 2025). "In DLBCL, overexpression of GPNMB promotes nuclear translocation of β-catenin by targeting YAP1, thereby enhancing the transcription of cyclin D1 and c-Myc, which in turn accelerates tumor proliferation." (PMID 41189944, 2025). "We stained the tumor tissue sections with five markers, α-SMA, GLUT1, CD68, ICAM1, and GPNMB, to exclude the possibility of simultaneous expression of ICAM1 and GPNMB by the same MDMs." (PMID 41174767, 2025). "GPNMB, which is consistently expressed in TSC/mTOR altered tumours, was positive in both components." (PMID 40590246, 2025). "Conversely, certain factors were downregulated in tumour cells, with END-1, MMP-2, and GPNMB showing a statistically significant reduction." (PMID 40869222, 2025). "Current evidence positions GPNMB at the intersection of immunometabolism and stromal remodeling, with its RGD and PKD domains serving as actionable targets to disrupt tumor-immune crosstalk." (PMID 41180454, 2025).